PTPRT (protein tyrosine phosphatase receptor type T)
Diseases named in the same sentence as PTPRT in open-access papers (continued):
Sharing a sentence is not in itself a finding about the gene and the disease.
tumor (44 papers, 2008 to 2025). "Consistently, PTPRD/PTPRT mutations are associated with tumor progression and a worse patient prognosis." (PMID 36248841, 2022). "Based on our analysis, it is obvious that a larger tumor was associated with a lower PTPRT expression level." (PMID 34414233, 2021). "In the further exploratory analysis, PTPRD/PTPRT mutation was significantly associated with increased tumor mutation burden and higher mRNA expression of JAK1 and STAT1." (PMID 34123798, 2021). "We then analyzed microRNA (miRNA) transcriptional targets of STAT327, and observed increased miR-21 and miR-181b in tumor samples carrying mutations in PTPRT or JAK2, while non STAT3 targets, such as miR-126, were similar." (PMID 31844068, 2019). "Interestingly, stratified survival analysis by tumor origin revealed preserved prognostic advantage of PTPRT mutations in NSCLC/SKCM/BRCA (Log-rank test, P = 0.012), but not in other subtypes." (PMID 40808963, 2025). "However, due to the unavailability of data, we were unable to analyze the association between PTPRT mutations and the efficacy of immunotherapy in other tumor types." (PMID 40808963, 2025). "Through the analysis of tumour genomic and clinical data, our previous study also supported that mutation events in PTPRT might serve as candidate markers of tumour early metastasis." (PMID 38216925, 2024). "Recent studies have reported that PTPRT mutations may be associated with the tumor mutation burden (TMB) and could provide clinically predictive implications for immune checkpoint inhibitor (ICI) therapies." (PMID 35789644, 2022). "Next, we explored the effect of PTPRT mutation on tumor prognosis." (PMID 35789644, 2022). "Furthermore, PTPRD/PTPRT mutations were associated with a higher tumor mutational burden, MSI score, and TCR score (P < 0.0001)." (PMID 36248841, 2022). "PTPRT might be associated with cell cycle and microtubule, and tumor infiltration in B cell and macrophage cell." (PMID 34414233, 2021). "Among these, PTPRK, PTPRM, and PTPRT are implicated as tumor suppressors, raising the possibility that they may also regulate ZNRF3 in certain cell types." (PMID 31934854, 2020). "Similarly, PTPRT mutation was also detected in AML using massively parallel sequencing technology to sequence the genomic DNA of both tumor and normal skin cells from a patient with AML." (PMID 31065022, 2019). "Among the four tumour cell lines, the expression of PTPRT was the highest in A549 and the lowest in H1975." (PMID 38216925, 2024). "Most MHC I molecules, including HLA-A, HLA-C, HLA-E, HLA-F, TAP1, TAP2, and TAPBP (all P < 0.05), were upregulated in PTPRD/PTPRT mutant patients, indicating enhanced anti-tumor immunity in PTPRD/PTPRT mutant patients." (PMID 36248841, 2022). "In line, PTPRM and PTPRT make part of the list of genes that are found deleted in tumors of the digestive tract." (PMID 36755664, 2022). "Third, we explored the effect of PTPRD/PTPRT mutations on TCR diversity, which was strongly associated with the anti-tumor response." (PMID 36248841, 2022). "In brief, PTPRD/PTPRT mutant patients had higher levels of immune cell infiltration, MHC I expression, and other immune signatures, indicating enhanced anti-tumor immunity in PTPRD/PTPRT mutant patients." (PMID 36248841, 2022). "In particular mutations in ERBB2, PTPRD, PTPRT, AURKB correlated with at least one of the clinical-pathological parameters under analysis such as node status (N), stage, tumor size (T) and/or presence of metastasis (M1)." (PMID 29844865, 2018). "Tumor change from baseline and the genetic alteration status for PTPRT/PTPRD are displayed in a waterfall plot." (PMID 30200630, 2018).
tumor (continued). "Increased expression of PTPRT in HepG2 cells with HBxΔ127overexpression was able to decrease the tumor weight and volume in vivo." (PMID 29558404, 2018). "Given the compelling evidence showing that PTPRT functions as a tumor suppressor, it is important to understand the signaling pathways regulated by this phosphatase." (PMID 27447856, 2017). "The PTPRT gene codes for a tyrosine phosphatase protein, receptor type T, and has been suggested that its product has tumor suppression functions." (PMID 23634293, 2013). "Considering that NSCLC and SKCM are two common tumor types for current immunotherapy, and the TMB was significantly increased in patients with PTPRT mutations, we hypothesized whether this mutation could evaluate the efficacy of immunotherapy." (PMID 40808963, 2025). "To investigate whether downregulation of PTPRT was associated with cell migration and invasion, we performed wound healing and transwell assays using PTPRT-knocked-down or overexpressed tumour cells." (PMID 38216925, 2024). "In addition, patients with PTPRT mutations harbored favorable ORR and survival outcomes in several tumor types." (PMID 35557959, 2022). "Recent research has shown that mutations in single genes, such as POLE, NLRP3, COL3A1, and PTPRT could predict tumor TMB and immunotherapeutic response." (PMID 35884556, 2022). "In addition, germline PTPRT and SLX4 mutations were significantly associated with smaller tumor sizes (both p < 0.05)." (PMID 35205332, 2022). "Previous review showed PTPRT as a tumor suppressor might be involved in cell cycle and cell adhesion." (PMID 34414233, 2021). "In addition to PTPRT/PTPRD deleterious alterations, univariate Cox regression identified the primary tumor site as a factor associated with PFS." (PMID 30200630, 2018). "Recently, several classical PTPs have been identified as potential tumor suppressors, including receptor PTPs such as DEP1 (densityenhanced phosphatase-1, encoded by PTPRJ), PTPκ (encoded by PTPRK) and PTPρ (encoded by PTPRT)." (PMID 25412184, 2014). "Finally, the minor allele of the SNP rs1040480, located in pRE1-49 within an intron of the tumour-suppressor PTPRT, reduces the affinity of REST." (PMID 22496669, 2012). "However, the impacts of PTPRT downregulation on tumour proliferation, invasion, and clinical interventions such as immune checkpoint inhibitor (ICI) therapies remained largely unknown." (PMID 38216925, 2024). "Together, these data suggest PTPRT may normally function as a tumor suppressor." (PMID 27447856, 2017). "Modulation of PTPRT expression in LUAD cell lines affected the expression of BIRC5 (survivin) significantly, as well as the proliferation, migration, and invasion of tumour cells." (PMID 38216925, 2024). "Among these, ERBB2, PTPRD, PTPRT, AURKB also correlated with node status, stage, tumor size and/or presence of metastasis." (PMID 29844865, 2018). "PTPRT/PTPRD dephosphorylate various signaling molecules, stabilize cell-cell adhesions and inhibit tumor migration." (PMID 30200630, 2018). "Receptor protein tyrosine phosphatase rho (PTPRT), a member of type IIB receptor-like PTPs subfamily, normally functions as a tumor suppressor." (PMID 24846175, 2014). "Consistently, the well‐known EMT pathway, which promotes tumor immune escape, was absent in the PTPRT mutant group (NES = −1.97, FDR = 0.026)." (PMID 34862763, 2022). "Although no copy number loss was observed for PTPRT, PTPRD heterozygous deletions occurred in four patients, in whom only one gene copy was observed in the tumor tissue." (PMID 30200630, 2018). "PTPRT belongs to the type IIB receptor-like PTPs and normally functions as a tumor suppresser." (PMID 24846175, 2014).
tumor (continued). "Collectively, our in-vitro results underscored the essential roles of PTPRT in inhibiting cell proliferation by affecting the expression of cell cycle-related genes like BIRC5, indicating that PTPRT downregulation could promote the malignant proliferation of tumour cells." (PMID 38216925, 2024).
neurological disorders (3 papers, 2017 to 2024). "PTPRT and ADAMTS are important genes related to spinal cord injury and neurological diseases." (PMID 39684322, 2024).
movement disorder (1 paper, 2021). Neurological conditions resulting in abnormal voluntary or involuntary movement, which may impact the speed, fluency, quality and ease of movement. "We suggested that DAB1 rs17115303 and PTPRT rs6030462 polymorphisms are genetic risk factors common to both diseases that directly or indirectly promote the accumulation of intraneuronal inclusions or neurodegeneration of DA and motor neurons, resulting in movement disorder." (PMID 34707478, 2021).
PTPRT also shares sentences with these, for which no sentence is quoted: neurodevelopmental disorder (5 papers); gastric adenocarcinoma (3); angiosarcoma (2); lung squamous cell carcinoma (2); prostate carcinoma (2); adenocarcinoma (1); astrocytoma (1); bacterial infections (1); brucellosis (1); cervical squamous cell carcinoma (1); colon (1); colorectal (1); colorectal adenocarcinoma (1); esophageal cancer (1); esophagogastric adenocarcinoma (1); Hand-foot syndrome (1); Hypercholesterolemia (1); Hyperglycemia (1); infection (1); LEOPARD syndrome (1); mesothelioma (1); mood disorder (1); Noonan syndrome (1); oligodendroglioma (1); pancreatic adenocarcinoma (1); rectum adenocarcinoma (1); rheumatoid arthritis (1); skin cutaneous melanoma (1); small cell lung carcinoma (1); tuberculosis (1).
A further 1 disease shares a sentence with PTPRT in 1 paper.